ARTN (artemin)
Diseases named in the same sentence as ARTN in open-access papers (continued):
Sharing a sentence is not in itself a finding about the gene and the disease.
Arrhythmia (1 paper, 2024). Any cardiac rhythm other than the normal sinus rhythm. "Although ARTN promotes sympathetic nerve fiber regeneration and branching, aiding neural recovery in the short term, prolonged elevation may exacerbate arrhythmias and ventricular dysfunction." (PMID 39726944, 2024).
Arthritis (1 paper, 2022). Inflammation of a joint. "Our results provide a molecular basis of arthritis pain linked with artemin/GFRα3 signaling and indicate that further work is warranted to investigate the neuronal plasticity and the pathways that drive pain in OA." (PMID 35153665, 2022).
breast tumors (1 paper, 2018). "However, only low levels of NRTN, ARTN, or their co-receptors were detected in primary breast tumors." (PMID 29608602, 2018).
cervical cancer (1 paper, 2022). A primary or metastatic malignant neoplasm involving the cervix. "Nonetheless, ARTN's significance in cervical cancer (CC) has not been studied." (PMID 36471885, 2022).
complication (1 paper, 2024). Any disease or disorder that occurs during the course of, or because of, another disease, treatment, or procedure. "Our findings demonstrated that genetically predicted higher levels of IL-12B and LIF likely increased the risk of T1D with renal complications, whereas higher levels of ARTN, CCL28, and S100A12 were related to a decreased risk." (PMID 39040677, 2024).
cyst (1 paper, 2022). A sac-like closed membranous structure that may be empty or contain fluid or amorphous material. "Specifically, these genes have been related to the diapause reproductive mode, such as BRCA1 and p8, and also with cyst resistance to stress, such as artemin, SGEG, Arp-CBP, and SGEG1 and SGEG2." (PMID 35432444, 2022). "The multiple regression analysis supports that five of these genes (SGEG, artemin, Arp-CBP, p8, and BRCA1) could be important predictor variables for cyst production in this population, given that all of them were included in the highest-ranking model." (PMID 35432444, 2022). "These genes participate at different levels, in the formation of the cyst chorion (e.g., SGEG and Arp-CBP), in the control of cellular division (e.g., BRCA1 and p8), or as molecular chaperones whose function is to avoid denaturation of the proteins (e.g., artemin, ArHsp21, ArHsp22, and p26)." (PMID 35432444, 2022).
developmental delay (1 paper, 2019). "It is noteworthy that some of the CNVs reported in ARTN, C2orf82, and PIDD1 are related to brain-specific and overall developmental delay at both fetal and postnatal stages." (PMID 31582733, 2019).
diabetic nephropathy (1 paper, 2024). "In the context of diabetic nephropathy, we postulated that ARTN may be instrumental in supporting the survival and repair of injured neurons or other cell types, while CCL28 is likely implicated in modulating inflammation, immune responses, and tissue repair mechanisms." (PMID 39040677, 2024).
disc degeneration (1 paper, 2023). "In the current study, the percentages of ARTN- and PSPN-expressing cells increased in the advanced stage of disc degeneration; however, the percentages of cells expressing their cognate co-receptors (GFRA3 and GFRA4, respectively) did not increase." (PMID 37958856, 2023).
glioma (1 paper, 2020). A benign or malignant brain and spinal cord tumor that arises from glial cells (astrocytes, oligodendrocytes, ependymal cells). "GDNF is a neurotrophic factor purified for the first time from a rat glioma cell line (B49) and belongs together with neurturin (NRTN), artemin (ARTN), and persephin (PSPN) to the family of GDNF ligands (GFL) belonging in turn to the superfamily of transforming growth factor β (TGF-β)." (PMID 33293946, 2020).
Infertility (1 paper, 2025). "MR results revealed genetic correlations between abnormal ADA, artemin, OSM, caspase 8, CXCL5, interleukin‐18, and LIFR levels and infertility." (PMID 40525280, 2025).
invasive carcinoma (1 paper, 2011). A carcinoma that is not confined to the epithelium, and has spread to the surrounding stroma. "TWIST1 can be regulated by multiple extracellular factors through PI3K/AKT, Wnt1 and NF-κB pathways in invasive carcinoma concordant with our observations that activation of AKT by ARTN leads to increased expression of TWIST1 in ER-MC cells." (PMID 22060274, 2011).
maturity-onset diabetes (1 paper, 2025). "Moreover, the GSVA showed that the low ARTN expression might induce IPF by activating ECM receptor interaction, ascorbate and aldarate metabolism, and maturity-onset diabetes of the young, while ARTN overexpression activated mismatch repair, DNA replication, and primary bile acid biosynthesis." (PMID 40093327, 2025).
motor neuron disease (1 paper, 2020). "ARTN appears to be involved in other neurological disorders, such as Hirschsprung and motor neuron disease." (PMID 32573073, 2020).
myalgic encephalomyelitis (1 paper, 2024). "This study aimed to assess plasma galectin-9 (Gal-9) and artemin (ARTN) concentrations as potential biomarkers to differentiate individuals with Long COVID (LC) patients with myalgic encephalomyelitis/chronic fatigue syndrome (ME/CFS) from SARS-CoV-2 recovered (R) and healthy controls (HCs)." (PMID 39386210, 2024).
myeloproliferative neoplasm (1 paper, 2025). A clonal hematopoietic stem cell disorder, characterized by proliferation in the bone marrow of one or more of the myeloid (i.e., granulocytic, erythroid, megakaryocytic, and mast cell) lineages. "Although splenic CD45-Ter119+ cells promote cancer progression by secreting artemin, it remains unclear whether these cells play an important role in myeloproliferative neoplasm (MPN)." (PMID 40302792, 2025).
neuropathy (1 paper, 2017). A disorder affecting the nervous system that manifests with pain, tingling, numbness, and/or muscle weakness. "Since ARTN was shown to restore expression of multiple neuronal markers in damaged sensory neurons, we studied the effects of BT13 on the expression of IB4, CGRP, and NPY in DRG of rats with experimental neuropathy." (PMID 28680400, 2017).
Pain (1 paper, 2020). An unpleasant sensory and emotional experience associated with actual or potential tissue damage, or described in terms of such damage. "For example, small molecule BT13 that mimics the effect of ARTN has been shown to selectively activate RET signalling and to support neurite growth in a similar way to ARTN, providing additional indication of the potential of ARTN for developing medications to treat neuropathic pain." (PMID 32573073, 2020).
Parkinson disease (1 paper, 2018). A progressive degenerative disorder of the central nervous system characterized by loss of dopamine producing neurons in the substantia nigra and the presence of Lewy bodies in the substantia nigra and locus coeruleus. "For example, ARTN has not been proved to be associated with T2D yet, but it is associated with Hirschsprung’s disease 1 and Parkinson disease, late–onset." (PMID 30497370, 2018).
polyp (1 paper, 2014). A usually exophytic mass attached to the underlying tissue by a broad base or a thin stalk. "53.9 and 51.3% of LSCC samples were positive for ARTN and GFRα1, respectively, whilst only 26.9% of normal squamous epithelium from patients with polyp were positive for ARTN and GFRα1 (P=0.015 and P=0.031, respectively)." (PMID 25120606, 2014). "The results revealed that the expression of ARTN and GFRα1 was significantly increased in LSCC compared with polyp tissue samples." (PMID 25120606, 2014).
pulmonary fibrosis (1 paper, 2023). Chronic progressive interstitial lung disorder characterized by the replacement of the lung tissue by connective tissue, leading to progressive dyspnea, respiratory failure, or right heart failure. "Combined with the previous literature, we speculate that ARTN might be implicated in the inflammatory cell infiltration in pulmonary fibrosis and promote the formation of IPF." (PMID 36930085, 2023).
Stroke (1 paper, 2024). Sudden impairment of blood flow to a part of the brain due to occlusion or rupture of an artery to the brain. "As far as ARTN is concerned, although its overexpression under hypoxia has been reported, its roles in stroke are unclear." (PMID 39684220, 2024).
tauopathies (1 paper, 2018). "Thissuggests that Artemin might be a suitable candidate forthe treatment of tauopathies, in particular AD, but onlyafter it has been rigorously investigated using cell-basedmodels of AD." (PMID 29105391, 2018).
viral encephalitis (1 paper, 2024). Encephalitis resulting from viral infection. "The results suggest that the inflammatory factors with a potential causal relationship with viral encephalitis are artemin, C-C motif chemokine 28, C-X-C motif chemokine 1, interleukin-10 and neurotrophin-3." (PMID 40008261, 2024).
viral infection (1 paper, 2021). "Of interest was the huge expression of Artemin in the secretome of infected cells, since this is the first evidence on the capability of human ECs to produce and secrete this potent pro-angiogenic factor upon viral infection." (PMID 34361874, 2021).
tumor (42 papers, 2011 to 2025). "Further, patients with cancer who received local tumor ionizing radiation (IR) alongside PD-1 therapy exhibited IR-mediated reduction of Ter-cells, artemin, and GFRα3 (an artemin signaling partner associated with tumor regression)." (PMID 39474425, 2024). "In summary, this study observed an association between tumor ARTN expression and clinical outcome for CRC patients." (PMID 34422665, 2021). "High expression of ARTN was observed to be associated with larger tumor size (P < 0.05) and higher clinical stage in HCC patients (P < 0.01)." (PMID 26675549, 2016). "Clinically, elevated expression of ARTN in HCC was associated with larger tumor size, faster relapse and shorter survival." (PMID 26675549, 2016). "The association of tumor expression of ARTN and GFRα1 with the clinicopathological features of LSCC was then investigated." (PMID 25120606, 2014). "Artemin (ARTN) has been implicated in promoting oncogenicity, tumor growth and invasiveness in diverse human malignancies." (PMID 23351331, 2013). "Furthermore, the expression of ARTN was demonstrated to be significantly associated with high tumor stage and poor survival." (PMID 25120606, 2014). "Cancer cells can release neurotrophic substances, including NGF and Artemin, to stimulate the development of nerve fibers toward tumor tissues." (PMID 40092993, 2025). "A prior study suggested that splenic Ter-cells(CD45-Ter119+CD71+ cells) in animals with advanced solid tumors secrete artemin (ARTN) to promote tumor progression." (PMID 40302792, 2025). "Late-stage CECs secrete artemin to promote tumor growth and invasiveness, and anti-artemin neutralizing antibody can inhibit tumor growth and increase the survival of tumor-bearing mice." (PMID 39474425, 2024). "In hepatic cancer, tumor-derived TGF-β contributes to the generation of splenic CD45−EPCs, which promote tumor progression via the neurotrophic factor artemin." (PMID 37208766, 2023). "Patients who received radio-immunotherapy showed that reduction of Ter-cells, artemin, and GFRα3, an artemin signaling partner, were related to tumor regression." (PMID 38028542, 2023). "Artemin promotes tumor progression and resistance to ICIs by activating the rearranged during transfection kinase." (PMID 38051531, 2023). "For example, tumor-induced CD45-Ter119+CD71+ erythroid progenitor cells (Ter cells) promote tumor progression by secreting artemin (ARTN), a neurotrophic peptide." (PMID 36532071, 2022). "It promotes tumor invasion and metastasis through the secretion of artemin into the blood as artemin promotes the proliferation of surviving cancer cells and increases tumor cells’ invasiveness." (PMID 36567722, 2022). "ARTN, a member of the glial cell line-derived neurotrophic ligand family, exerts oncogenic effects on a wide range of solid tumors, including tumor growth, metastasis, and angiogenesis." (PMID 36452159, 2022). "The specific mechanism by which artemin promotes tumor growth and distant metastasis also remains undetermined." (PMID 36567722, 2022). "In hepatocellular carcinoma, Artemin inhibits tumor cell apoptosis and promotes its migration by upregulating the expression of TROIBP and ITGB5." (PMID 35799264, 2022). "In the mouse models, Ter-cell derived artemin promoted cancer progression, while artemin knockout, pharmacological inactivation, or tumor-restricted knockdown of its receptor GFRα3 delayed cancer progression." (PMID 36561751, 2022). "In these cancers, ARTN expression is positively correlated with tumor size, invasiveness and metastasis." (PMID 34422665, 2021). "While immunomodulatory early-stage EPCs accumulate in the spleen and intensively infiltrate TME, tumor-promoting late-stage EPCs are detected mainly in the spleen where they secrete artemin into circulation." (PMID 33669537, 2021). "It was observed that high tumor expression of ARTN in CRC also predicted relapes and overall survival rates." (PMID 34422665, 2021).
tumor (continued). "Anti-artemin neutralizing antibody inhibits tumor growth and increases the survival of tumor-bearing mice." (PMID 33669537, 2021). "Consistently, in vivo depletion or deficiency of ARTN inhibits the growth of HCC and abolishes tumour‐promoting ability of erythroblast‐like cells." (PMID 32573073, 2020). "We next determined if the worse survival outcome in patients with tumors with co-expression of either GFRα1 or GFRα3 and ARTN was restricted to tumor subtypes." (PMID 23351331, 2013). "It has been reported that forced expression of ARTN promotes tumor growth by increased proliferation and survival." (PMID 23351331, 2013). "For instance, artemin enhances transcription of bcl2 – leading to it's up regulation and thereby augments tumor growth in human non-small cell lung carcinomas." (PMID 22891163, 2012). "Such co-ordinate regulation of tumor growth and metastasis warrants consideration of the use of therapeutic strategies inhibitory to ARTN activity in ER-MC." (PMID 23185544, 2012). "In summary, we have demonstrated herein that ARTN promotes de novo tumor angiogenesis mediated in part by increased VEGF-A expression." (PMID 23185544, 2012). "Forced expression of ARTN produced a larger, locally invasive tumour mass with tumour emboli that produced distant metastasis." (PMID 22060274, 2011). "Increasing evidence had demonstrated a connection between high expression of ARTN and tumor relapse, metastasis and poor prognosis." (PMID 21453483, 2011). "In accordance, we have observed that forced expression of ARTN in ER-MC cells increased a sub-population of cells with cancer stem cell-like behavior and enhanced in vivo tumor initiating capability (manuscript in preparation)." (PMID 22060274, 2011). "Cancer cells release neurotrophins like Nerve Growth Factor (NGF), Brain-Derived Neurotrophic Factor (BDNF), Glial Cell Line-Derived Neurotrophic Factor (GDNF), and artemin (ARTN), which bind to receptors on nerve cells, promoting neurite outgrowth toward the tumor." (PMID 40909268, 2025). "MET, GPI, ANGPTL4, HSPA5, TGFA, MIF, and ARTN were significantly up-regulated in tumor samples." (PMID 36447119, 2023). "Increased ARTN expression by tumor cells is an essential marker of cancer progression, as autocrine and paracrine processes may enhance invasiveness, metastasis, carcinogenesis, and drug resistance to certain chemotherapies." (PMID 36471885, 2022). "The neurotrophic factor Artemin (ARTN) is involved in tumor proliferation and metastasis." (PMID 36471885, 2022). "CD45− EPCs promote tumor invasion and metastasis by secreting artemin." (PMID 36567722, 2022). "In addition, in cancer patients and tumor-bearing mice, radiotherapy reduced the level of Artemin in serum and the expression of GFRα3 in tumor tissues." (PMID 35799264, 2022). "Importantly, increase in serum artemin levels and elevated tumor expression of GFRα3 were also observed in human HCC patients and correlated with poor prognosis." (PMID 36561751, 2022). "Furthermore, we first identified ARTN from RNA seq data and observed that ARTN expression level increased when E2 treatment promoted tumor growth in ovariectomized mice." (PMID 34257587, 2021). "Collectively, these observations demonstrate that in cancer patients, early-stage CD45+ EPCs may suppress the immune response, and late-stage CD45− EPCs may promote tumor growth by the secretion of artemin." (PMID 33669537, 2021). "Late-stage EPCs promote tumor growth and invasiveness via the secretion of artemin." (PMID 33669537, 2021). "Thus, the reduction in EPC expansion reduces the increase in the artemin concentration in the serum and decreases tumor growth." (PMID 33669537, 2021). "Recently, a role of ARTN in tumorigenesis, tumour metastasis and drug resistance is emerging." (PMID 32573073, 2020). "Hence, ARTN promotes the metastatic properties and tumor-initiating capacity of HCC cells by AKT modulation of factors involved in EMT and stemness." (PMID 26675549, 2016).